IRS2 (insulin receptor substrate 2)
Diseases named in the same sentence as IRS2 in open-access papers (continued):
Sharing a sentence is not in itself a finding about the gene and the disease.
Insulin resistance (continued). "High insulin concentration in insulin resistance stimulates lipogenesis through the activation of sterol regulatory element-binding protein 1 (SREBP-1c), which inhibits insulin receptor substrate 2 (IRS-2) mediated insulin signaling." (PMID 29085434, 2017). "Furthermore, in hepatocytes with insulin resistance, SREBP-1c expression is increased, while the expressions of IRS2 and insulin-induced Akt phosphorylation are significantly decreased." (PMID 27247938, 2016). "In muscle, insulin resistance seems to attenuate predominantly IRS1-dependent GLUT4 translocation and glucose uptake, though some reports suggest that IRS2-dependent insulin signaling cascade could also be involved in glucose metabolism in myocytes." (PMID 27247938, 2016). "Here, we showed that PA reduced insulin‐stimulated tyrosine phosphorylation of insulin receptor substrate 2 and decreased insulin‐stimulated uptake of the fluorescent glucose analog 2‐NBDG, confirming that insulin resistance occurred in PA‐treated H4IIEC3 cells." (PMID 27833848, 2016). "We demonstrate that hepatic Irs2-knockout mice develop ‘selective insulin resistance', whereas mice lacking in Irs1, or both Irs1 and Irs2, develop ‘total insulin resistance'." (PMID 27708333, 2016). "Mice lacking in hepatic Irs2 develop ‘selective insulin resistance', whereas mice lacking in hepatic Irs1, or both hepatic Irs1 and Irs2 develop ‘total insulin resistance'." (PMID 27708333, 2016). "Mice lacking IRS-2 develop diabetes due to peripheral insulin resistance, failed hypothalamic regulation of appetite and β-cell insufficiency." (PMID 23560040, 2013). "Studies indicate that insulin resistance can be induced by stimulating the degradation of important molecules in the insulin signaling pathway, in particular the insulin receptor substrate proteins IRS1, IRS2 and the kinase AKT1 (Akt)." (PMID 19007436, 2008). "In addition, other cell culture models of insulin resistance, such as osmotic stress or chronic exposure to insulin or IGF1 (IGF-1), have been shown to promote degradation of IRS2 in NIH3T3 cells." (PMID 19007436, 2008). "However, mice where Irs2 is silenced, specifically in the liver, show selective insulin resistance, in which insulin no longer suppresses the process of gluconeogenesis but continues to activate lipogenesis." (PMID 40426854, 2025). "Furthermore, in a recent study, HFD promoted the activation of aryl hydrocarbon receptor (AhR) by exosome-derived PCs, resulting in the repressed expression of insulin receptor substrate 2 (IRS2) and its downstream genes PI3K and AKT, leading to insulin resistance." (PMID 38706565, 2024). "Furthermore, PDB extracts promoted the expression of insulin receptor β (IRβ), insulin receptor substrate-1 (IRS-1), insulin receptor substrate-2 (IRS-2), and glucose transporter-4 (GLUT4) in the liver to enhance insulin sensitivity and reduce insulin resistance." (PMID 37849729, 2023). "Furthermore, peripheral insulin resistance might also be accompanied by central insulin resistance, IGF-1 resistance, and IRS-1 and IRS-2 dysfunction, presumably as a consequence of Aβ oligomers further contributing to cognitive decline." (PMID 35615716, 2022). "Likewise, levels of genes involved in glucose metabolism such as IRS-1, IRS-2, and GLUT-4 were reduced upon obesity or arthritis induction, either alone or combined, which may facilitate an insulin resistance state." (PMID 34721412, 2021). "Wu found that BSJPHX principle could significantly improve the clinical symptoms of TCM in patients with T2DOP, effectively reduce blood glucose and glycosylated hemoglobin, fasting insulin level and insulin resistance index, and improve BMD and serum IGF-1, IRS-1, IRS-2 levels." (PMID 33761702, 2021). "Mice with global ablation of Irs2 show IR in the liver but not in skeletal muscle and present a diabetes-like phenotype, while the decreased ratio of IRS1:IRS2 has been implicated in selective hepatic insulin resistance in T2D and NAFLD." (PMID 34046015, 2021).
Insulin resistance (continued). "It was reported that ablation of IRS-2 in mice leads to many type 2 diabetes hallmarks, including peripheral insulin resistance conjoined with a lack of compensatory beta cells expansion, ending up with hyperglycemia and diabetes, and followed by premature death." (PMID 34912223, 2021). "Liver-specific Irs1-knockout mice (LIrs1KO) failed to exhibit insulin resistance during fasting, but showed insulin resistance after refeeding; conversely, liver-specific Irs2-knockout (LIrs2KO) mice exhibited insulin resistance during fasting, but not after refeeding." (PMID 33923817, 2021). "Insulin resistance in the absence of hyperglycemia found in the HL group in this study may have occurred due to the ability of IRS-2 to partially compensate for the absence of IRS-1." (PMID 32881885, 2020). "Consequently, mice lacking Irs2 exhibit selective insulin resistance and specific knockout of Irs2 in hepatocytes activates gluconeogenic pathways." (PMID 32710190, 2020). "These investigations suggest that reduced expression of KLF4 triggered by a high-fat diet in our mouse model (IR+/-IRS1+/-ApoE-/-) may mediate down-regulation of IRS2 and TSC2 expression thereby impairing insulin signaling in adipocytes and promoting insulin resistance." (PMID 30240435, 2018). "Interestingly, vaspin treatment reversed these effects, indicating that vaspin could inhibit the serine phosphorylation level of IRS-2 in INS-1 cells induced by palmitic acid, further improved the insulin resistance of INS-1 cells." (PMID 29240812, 2017). "Other studies also suggest that muscle IRS1, but not IRS2, is reduced in insulin resistance." (PMID 27247938, 2016). "Moreover, mice lacking both Irs1 and Irs2 failed to develop ‘selective insulin resistance' despite deletion of Irs2." (PMID 27708333, 2016). "Moreover, NAFLD leads to hepatic insulin resistance by stimulating gluconeogenesis, and upregulated SREBP-1c may suppress IRS-2-mediated insulin signaling generating a feedforward machinery to further stimulate or worsen NAFLD." (PMID 26504484, 2015). "Besides peripheral insulin resistance, this alteration may be present in the brain accompanied by IGF1 resistance, and IRS-1 and IRS-2 dysfunction, potentially triggered by Aβ oligomers and cognitive decline." (PMID 25346723, 2014). "Another study has shown that the mechanism by which FFA induces insulin resistance involves the intramyocellular and intrahepatocellular accumulation of triglycerides and diacylglycerol, which then reduce tyrosine phosphorylation of insulin receptor substrate-1 (IRS-1) and IRS-2." (PMID 23983807, 2013). "We therefore hypothesise that signalling changes reported here occur as a direct result of Irs2 deletion in kidney, and not as a result of insulin resistance." (PMID 20604929, 2010). "Likewise, down-regulation of Irs2 and the glucose transporter GLUT2 (Slc2a2) in pancreatic islets confirms previous reports and reflects deterioration of beta cell function in the course of insulin resistance and diabetes." (PMID 18590522, 2008). "However, the expression of IRS-2 was not restored by myocardin upregulation, and serum insulin levels suggested that myocardin upregulation may not alter systemic insulin resistance." (PMID 38505620, 2024). "The degree of rescue of dedifferentiation by homozygous CDK4-R24C observed in this study was surprisingly complete, especially given the lack of improvement in insulin resistance, suggesting that loss of CDK4/cyclinD2 activity may be a primary cause of β cell failure in IRS2-null mice." (PMID 37712417, 2023). "In addition, the expression of p-IRS2 and FOXO1 increased (p < 0.05, p < 0.0001, p < 0.001), and the expression of p-AKT decreased (p < 0.01) in the 15w-Z group, compared with the 15w-L group, confirming that insulin resistance appeared in the brain of 15-week-old ZDF rats." (PMID 34485269, 2021).
Insulin resistance (continued). "However, although IRS2/AKT may also play a role in insulin resistance, it is not enough to resist the role of IRS2/AKT activation in promoting NAFLD and HCC." (PMID 32169080, 2020). "Signaling of insulin occurs via insulin receptor substrate 2 (IRS2) and is not suppressed during insulin resistance, while signaling via IRS1 for counterregulatory mechanisms, including local NO production, is impaired." (PMID 32819363, 2020). "More importantly, cardiac insulin resistance is a feature of human HF, and IRS1, but not IRS2, was found to be downregulated in failing human hearts." (PMID 32223896, 2020). "Ablation of the IRS-2 gene produced a diabetic phenotype; Mice lacking IRS-2 displayed peripheral insulin resistance and β-cell dysfunction characterized by a 50% reduction in β-cell mass." (PMID 26919700, 2016). "Impaired function of IRS2 has been related to a defective activation of phosphoinositide 3-kinase (PIK3), a reduction in glucose uptake and insulin resistance in certain studies but not in others." (PMID 20540717, 2010). "Hepatic insulin resistance represents a paradox in hepatic steatosis since insulin receptor activation of insulin receptor substrate-1 (IRS-1) is active and accounts for increased DNL, yet insulin does not inhibit insulin receptor substrate-2, which controls liver gluconeogenesis." (PMID 20300478, 2009).
diabetes (107 papers, 2003 to 2026). "We have found the antisense RNA encoded in the IRS2 locus in mice and humans, which is upregulated in feeding, obesity, and diabetes and upregulates PPARγ expression, leading to increased hepatic fat accumulation." (PMID 39513056, 2024). "Replacing both endogenous alleles of Cdk4 with Cdk4-R24C prevented diabetes in IRS2-null male mice by rescuing β cell mass, function, and differentiation and restoring cytoplasmic FOXO1 location and nuclear PDX1 abundance in β cells in vivo." (PMID 37712417, 2023). "A compound knock out mouse model demonstrated that PTP1B global deficiency decreased severe diabetes caused by insulin receptor substrate 2 deletions." (PMID 34093192, 2021). "Similar to the INSR gene mentioned earlier, IRS-2 is an insulin receptor substrate that is highly associated with diabetes and obesity and negatively controls alternative macrophage activation and allergic inflammation of the lungs." (PMID 32512817, 2020). "Irs2 is a paralog of Irs1 encoding insulin receptor substrate-2, which is similarly phosphorylated by insulin receptor kinase and linked to diabetes, but additionally has haplotypes associated with severe obesity." (PMID 33330474, 2020). "In the current study, we determined the association of the variants of IRS-1 Gly972Arg (G972R) and IRS-2 Gly972Arg (G72R) with diabetes." (PMID 31404179, 2019). "A previous study using IRS2−/− mice suggested that IRS2-deficient mice developed diabetes as a result of severe IR paired with β-cell failure and showed higher lipogenic enzyme FAS and hepatic lipid levels." (PMID 30862092, 2019). "On the other hand, the disruption of IRS2 impaired peripheral insulin signaling and pancreatic β-cell function, and these incomplete signaling pathways finally caused diabetes." (PMID 28282409, 2017). "In conclusion, diabetes in IRS2-deficient male mice is associated with increased oxidative stress and apoptosis in the hypothalamus." (PMID 27013528, 2016). "Sequence polymorphisms in the human IRS2 locus have been associated with obesity, type 2-diabetes-mellitus (T2DM) or its complications, aspects of schizophrenia and IgE immune responses." (PMID 26178806, 2015). "Restoration of Irs2 specifically to β-cells has been demonstrated to prevent the development of diabetes caused by IRS-2 deficiency and diet-induced obesity." (PMID 23560040, 2013). "In mice, deletion of Irs1 is associated with profound growth retardation and increased longevity whereas Irs2-deficiency causes diabetes and female infertility." (PMID 23741292, 2013). "The loss of Irs2 causes diabetes in mice due to pancreatic beta cell insufficiency and most male Irs2-deficient mice die from diabetic complications by 16 weeks of age." (PMID 23741292, 2013). "A previous study in IRS2 null mice had demonstrated that the severe diabetes associated with markedly increased apoptosis and reduced proliferation of islet β-cells was reversed when crossed with Gsk3β haploinsufficient mice." (PMID 21541314, 2011). "We postulated that if loss of cyclin D2/CDK4 activity in β cells is a primary cause of diabetes in IRS2-null mice, then activating CDK4 in vivo might counteract the diabetogenic phenotype in these mice." (PMID 37712417, 2023). "Irs-2 deletion in mice causes diabetes and has a sexually dimorphic phenotype." (PMID 34220716, 2021). "Durable epigenetic modifications are programmed by maternal overnutrition—in C57BL6/J mice, hepatic insulin receptor substrate 2 (Irs2) and mitogen-activated protein kinase 4 (Map2k4) gene methylation occurred in progeny, thereby increasing their susceptibility to diabetes." (PMID 33158303, 2020). "In a previous study, we found activation of hypothalamic inflammatory pathways that differentially correlate with the absence or presence of diabetes in IRS2-deficient mice, suggesting that the inflammatory process could be related to the onset of disease." (PMID 27013528, 2016).
diabetes (continued). "Indeed, polymorphisms of IRS1 and/or IRS2 have shown the significant associations with diabetes, glucose levels, and obesity, as well as with cancers, along with IGF signaling regulator genes." (PMID 27483248, 2016). "Insulin receptor substrate-2-deficient (IRS2−/−) mice are considered a good model to study the development of diabetes because IRS proteins mediate the pleiotropic effects of insulin-like growth factor-I (IGF-I) and insulin on metabolism, mitogenesis and cell survival." (PMID 27013528, 2016). "Furthermore, IRS2-deficient mice recapitulate the fulminate onset of human diabetes because a significant proportion of these mice develop diabetes abruptly at 12-16 weeks of age." (PMID 27013528, 2016). "A couple of studies reported that the association of the Asp1057 allele in IRS-2 with type 2 diabetes may be mediated by interaction of the polymorphism with obesity on several diabetes-related traits." (PMID 25310961, 2014). "The reproductive capacity of Irs2 males paired with wild-type females decreased drastically once hyperglycemia was detected, most likely as a consequence of the metabolic alterations of uncontrolled diabetes including weight loss, polydipsia, and polyuria." (PMID 23741292, 2013). "However, previous studies have demonstrated that Irs2-deficient males are adequate breeders, at least prior to the onset of severe diabetes." (PMID 23741292, 2013). "The deficit in hippocampal LTP correlates well to previous studies carried out on experimental models of diabetes, in this case with the advantage that the restricted loss of IRS-2 in neurons eliminates hyperglycaemia as a confounding systemic complication associated with diabetes." (PMID 22383997, 2012). "Insulin receptor substrates 2 (IRS2) is the primary isoform of insulin receptor substrate expressed in ECs, dysregulation of IRS1/IRS2 contributes to the metabolic disorder, obesity and diabetes." (PMID 40443971, 2025). "IRS1 and IRS2 in the insulin signaling pathway are dysregulated in diabetes mellitus, so they need to work in concert to maintain normal glucose metabolism and insulin sensitivity." (PMID 40747301, 2025). "The expression of IRS2 was also decreased in vascular dementia, as well as human metabolic traits such as diabetes mellitus and obesity." (PMID 39061961, 2024). "Phosphorylation of IRS-2 at Ser731 has been shown to be significantly increased in nervous tissue in diabetes, contributing to the development of resistance to insulin." (PMID 39057034, 2024). "In summary, we report the discovery that CDK4 promotes insulin signaling and FOXO1 degradation in the pancreatic β cell, derepressing Pdx1 expression and rescuing diabetes in Irs2–/– mice." (PMID 37712417, 2023). "As a result, IRS-related signaling by IGF1R, which is directly related to diabetes, was derived (IRS2, IGF1R, PIK3CD, and PIK3CB)." (PMID 37608331, 2023). "Taken together, these data suggest that the rescue of diabetes in IRS2-null mice by Cdk4-R24C was due to correction of insulin deficiency rather than insulin responsiveness." (PMID 37712417, 2023). "In earlier studies, acute hepatocyte-specific HIF-P4H-3 loss has been shown to improve insulin sensitivity and ameliorate diabetes by specifically stabilizing HIF2α and the upregulation of Irs2 transcription and insulin-stimulated protein kinase B activation." (PMID 35787374, 2022). "These proteins are important insulin pathway-related factors, and the deletion of IRS1 and IRS2 genes leads to the development of diabetes in mice." (PMID 34497509, 2021). "Diabetes reduced Irs2 gene expression in parents and their offspring; this reduction was observed only in female offspring." (PMID 34848753, 2021). "It is assumed that IRS1/IRS2 dysregulation plays a crucial role in the development of obesity and diabetes." (PMID 34830458, 2021).